TRPV4 (transient receptor potential cation channel subfamily V member 4)
Diseases named in the same sentence as TRPV4 in open-access papers (continued):
Sharing a sentence is not in itself a finding about the gene and the disease.
tumor (continued). "Studies show that calcium channels like transient receptor potential melastatin 7 (TRPM7) and transient receptor potential cation channel subfamily V member 4 (TRPV4) are key players in supporting endothelial cell migration, contributing to angiogenesis, which is crucial for tumor growth." (PMID 39769488, 2024). "Although developing TRPV4-based antitumor drugs continues to be challenging, therapeutic benefits could emerge from TRPV4’s potential inhibitory effect on tumor onset and progression, enhancing the prognostic index." (PMID 38730655, 2024). "Modulating the activity of these channels could lead not only to the inhibition of tumor cells’ growth but also to the increased efficacy of existing therapies on TRPV4-overexpressing cells." (PMID 38730655, 2024). "The high expression of TRPV4 is characteristic of epithelial tissues and of the tumor counterpart, these receptors responding to heat, osmotic changes and mechanical stretching, inducing the influx of Ca2+, TRPV4 also regulates cell volume by interacting with F-actin." (PMID 39015505, 2024). "In addition, tumors have been shown to release exosomes that inhibit the mechanosensitive ion channel transient receptor vanilloid 4 (TRPV4), whose expression and activity is significantly reduced in tumor endothelial cells (TECs)." (PMID 38667297, 2024). "In addition, activation of TRPV4 normalizes tumor vasculature, thereby delaying malignant progression." (PMID 38505262, 2024). "TRPV4 expression in human GBM tissues correlates with both tumor grade and poor survival, suggesting that TRPV4 could be an attractive therapeutic target and biomarker for GBM." (PMID 37456742, 2023). "Notably, after tumor cell inoculation, TRPV4 expression increased from day 7 while TET1 expression started to rise on day 3 only." (PMID 37190609, 2023). "Moreover, we analyzed the correlation of two members of the TRP family, namely TRPV4 and TRPC4, with tumor mutational burden (TMB) and microsatellite instability (MSI), as well as the genes related with immune activation." (PMID 36830651, 2023). "Firstly, the underlying mechanism of the 6 identified PGRs, especially CITED2, EXOC6B, MIA2, and TRPV4, in OV progression and tumor immune microenvironment remained largely unknown, which needs stepwise investigation." (PMID 37730669, 2023). "Thus, endothelial TRPV4 emerges as a subtle modulator of vascular integrity and an inhibitor of tumor angiogenesis, given that the deletion of TRPV4 promotes tumor angiogenesis, growth, and metastasis." (PMID 37892239, 2023). "Thus, TRPV4 plays a role in several tumor-related mechanisms, such as proliferation, apoptosis, angiogenesis, migration and invasion." (PMID 37762011, 2023). "Based on these findings, we hypothesized that TRPV4 could likely regulate tumor metastasis through Src-cortactin signaling." (PMID 36499486, 2022). "In summary, TRPV4 may be involved in preventing and treating OV by regulating the tumor immune microenvironment." (PMID 35813831, 2022). "TRPV4 knockdown also decreased the growth of tumor xenografts in vivo." (PMID 36619170, 2022). "The combination of an activator of TRPV4 with cisplatin could increase the delivery of cytotoxic agents to the tumor site and significantly suppress tumor growth." (PMID 35173539, 2022). "Moreover, at the tumor level, TRPV4 gene expression was lower in the more aggressive fusion+ than in fusion− tumors, opposite to the DDR1 expression trend." (PMID 35957513, 2022). "Both ECM itself and ECM stiffening-induced mechanical stimuli may activate cell membrane receptors and mechanosensors such as integrin, Piezo1 and TRPV4, thereby modulating the malignant phenotype of tumor and stromal cells." (PMID 35331296, 2022). "However, increased levels of AQP4 and AQP4/TRPV4 co-expression were detected in most tumors with larger edema whereas upregulation of AQP4 was found in peri-tumor tissue." (PMID 33538957, 2021).
tumor (continued). "Furthermore, the overexpression of TRPC1 has been discovered to be correlated with small tumors low proliferating (Grade 1), whereas TRPV4 is correlated with tumor grade, tumor size, and patient overall survival." (PMID 34209733, 2021). "To elucidate this, previously, we found that tumor cell conditioned media (TCM) causes normal human endothelial cells (hNEC) to transform into a human tumor endothelial cell-like phenotype (hTEC) via TRPV4 downregulation, leading to abnormal tube formation in vitro." (PMID 35004649, 2021). "Notably, we have shown that TRPV4 is downregulated in tumor endothelial cells and that pharmacological activation of these channels normalizes the tumor vasculature and improves drug delivery." (PMID 35004649, 2021). "In our study, we assessed TRPV4 expression using data from The Cancer Genome Atlas (TCGA) and the Genotype-Tissue Expression (GTEx) database and found that TRPV4 was differentially expressed in 25 tumor types." (PMID 34262942, 2021). "It is reported that TRPV4 negatively regulates tumor angiogenesis and tumor vessel maturation." (PMID 33981725, 2021). "Similarly, TRPV4 is also required for actin remodeling in endothelial cells and thus promotes angiogenesis and tumor progression." (PMID 32211326, 2020). "This TRPV4-dependent switch in E-cadherin expression may also lead to increased dissociation from the tumour mass." (PMID 32228863, 2020). "Furthermore, in a xenograft mouse model system, the blockage of TRPV4 was shown to decrease tumor size and weight compared to the control group." (PMID 32182937, 2020). "TRPV4 has been the first TRP channel to be clearly implicated in tumor angiogenesis, although it can have both pro-angiogenic and anti-angiogenic effects depending on tumor type." (PMID 33132914, 2020). "Furthermore, under inflammatory circumstances, T cell TRPV4 facilitates the release of interferon-γ, which represents an important mediator of tumor immune escape." (PMID 33317522, 2020). "Collectively, targeting TRPV4 can simultaneously act on tumor cells and their “hijacked” immune cells, reduce the production of inflammatory factors, and finally ameliorate the inflammatory microenvironment for tumor metastasis." (PMID 31235786, 2019). "TRPV4-mediated extracellular Ca2+ entry has been implicated also in neovascular diseases, such as PAH and cancer (see Section Remodeling of Endothelial TRP Channels Promote Aberrant Tumor Vascularization)." (PMID 32038296, 2019). "Conversely, TRPV4 could be inhibited or stimulated to interfere with or normalize tumor vasculature in, respectively, BC and LLC." (PMID 32038296, 2019). "Notably, tumor vasculature in TRPV4 KO mice presented a greater percentage of hyper-permeable, pericyte-free and dilated microvessels, which are known to temper the therapeutic outcome of anticancer treatments." (PMID 32038296, 2019). "Therefore, the main goal of this study is to show that tumor cell conditioned media (TCM) can induce downregulation of TRPV4 channels." (PMID 31921855, 2019). "Therefore, TRPV4 activation seems relevant to normalize tumor angiogenesis via modulation of Rho/Rho kinase pathway." (PMID 30559679, 2018). "In tumor-derived endothelial cells TRPV4 expression levels are lowered." (PMID 29772843, 2018). "Furthermore, stimulation of TRPV4 promotes, not only tumor cell migration, but also neovascularization, suggesting a possible relationship with hematogenous dissemination." (PMID 28081185, 2017). "Finally, using a syngeneic tumor model revealed that TRPV4 activation, with GSK, significantly reduced endothelial cell proliferation in vivo." (PMID 26388427, 2015). "Some studies have shown that the transient potential receptor vanilloid 4 (TRPV4) channel in endothelial cells plays an important regulatory role in tumor growth and metastasis, as it regulates tumor angiogenesis and vascular integrity, inhibiting tumor growth and metastasis." (PMID 40438141, 2025).
tumor (continued). "Interestingly, in breast and renal-derived tumor endothelial cells, TRPV4 is upregulated." (PMID 36837670, 2023). "While other pathways may be involved in promoting vessel maturation, the data obtained in this study with regards to the expression of Ang-1 and Tie-2 genes suggest that TRPV4 activation in OSCC may promote the maturation of tumor vessels via modulation of the Ang-1/Tie-2 pathway." (PMID 36143906, 2022). "Endothelial cells with diminished levels of TRPV4 exhibit reduced mechanosensitivity, which increases cell migration on stiffer substrates and decreases VE-cadherin at cell-cell junctions, leading to abnormal angiogenesis, enhanced tumor growth, and enhanced lung metastasis." (PMID 36158191, 2022). "It is speculated that the tumor microenvironment can easily activate TRPV4." (PMID 36499486, 2022). "Besides Piezo1, another mechano-sensitive ion channel TRPV4 is involved in tumor progression." (PMID 35331296, 2022). "The expression of TRPV4 may be an important indicator of anti-tumor activity." (PMID 35813831, 2022). "Importantly, high TRPV4 expression often indicates tumor immunosuppression, which may render immune checkpoint inhibitors unsuitable for treatment." (PMID 34262942, 2021). "Despite these reports, the role of TRPV4 in most tumor types remains unclear." (PMID 34262942, 2021). "Inflammatory factors released in the tumor microenvironment, such as IL-1, IL-8, arachidonic acid, and phosphatase A2, as well as interstitial plasticity changes can promote opening of the tumor TRPV4, at which point the inflammatory factor release is reinforced by cascade amplification." (PMID 31235786, 2019). "In addition, TRPV4 has also been significantly correlated with tumor angiogenesis." (PMID 31235786, 2019). "Hypothetically, low expression of TRPV4 in skin cancer affects the release of ATP and autocrine communication between keratinocytes by regulating Ca2+ homeostasis, then decreasing extracellular Ca2+ concentration, keeping cells intact and ultimately inducing tumor formation." (PMID 31235786, 2019). "TRPV4 is critical for tumor angiogenesis, but it may affect various tumors differently." (PMID 31235786, 2019). "Therefore, it is of great significance to clarify the mechanism of TRPV4 in tumor metastasis." (PMID 31235786, 2019). "Regardless of burgeoning studies on the roles of TRPV4 in tumors, its differential expressions in different tumor tissues and the underlying mechanisms are still largely unknown." (PMID 31235786, 2019). "In addition, TRPV4 activation may selectively inhibits tumor endothelial cell proliferation via inhibition of ERK1/2 phosphorylation." (PMID 31235786, 2019). "Therefore, remodeling of TRPV4-mediated Ca2+ entry may be used to effectively target tumor vascularization, although the most effective approach may depend on the tumor type." (PMID 29324706, 2018). "In addition, endothelial TRPV4 has been shown to regulate tumor angiogenesis." (PMID 29293584, 2018). "Depletion of Arhgef2 (GEF-H1) and Arhgef17 (Tumour Endothelial Marker 4, TEM4) resulted in a reduced lamellipodia protrusion speed similar to that seen with TRPV4 inhibition." (PMID 40196692, 2025). "To investigate the expression of TET1 and TRPV4 in L4–6 DRG of BCP rats, we performed qPCR and Western blotting at days 0, 3, 7, 14, and 21 after tumor cell inoculation." (PMID 37190609, 2023). "Considering the results of the differential expression of TRP family genes between tumor and para-carcinoma tissues and RNAss, DNAss, and TME scores, we selected TRPC4 and TRPV4 as the representative TRP family genes." (PMID 36830651, 2023). "Pharmacological activation of TRPV4 by GSK1016790A in TECs normalizes tube formation in vitro and tumor angiogenesis in vivo, which reduces tumor growth in combination with cisplatin." (PMID 37864030, 2023). "The results show that TRPV4, MCOLN1,and TRPM5 are expressed differently between normal and tumor tissues." (PMID 38188686, 2023).
tumor (continued). "Differential expression analysis showed that the expression of TRPC7, TRPV4, and other TRP family members was significantly different between tumor and normal tissues." (PMID 35813831, 2022). "Having predicted that TRPV4 is closely related to immune regulation pathways through GSEA analysis, we focused on the infiltration of immune cells in the tumor microenvironment." (PMID 34262942, 2021). "Various potential risk factors contribute to the formation of PTBE, such as tumor-brain barrier disruption, tumor size, location, tumor margin shape, AQP4/TRPV4 channel co-expression, and vascular endothelial and lymphatic dysfunction." (PMID 34707993, 2021). "However—in many other tumor types—the function of TRPV4 remains unclear." (PMID 34262942, 2021). "In this study, we evaluated the expression of TRPV4 in GBM and revealed its role as a tumor promoter, which role is mediated by Cdc42/N-wasp activation and promotion of cellular protrusion formation." (PMID 32843668, 2020). "In addition, with the use of a TRPV4-specific antagonist and agonist, Fang and colleagues showed that TRPV4 is crucial for HCC cell viability and that its inhibition could cause anti-tumor effects through modulation of the expression of apoptosis-related molecules." (PMID 32182937, 2020). "Specifically, we have shown that the pharmacological activation of TRPV4 with GSK normalizes the tumor vasculature and, in combination with Cisplatin, reduces tumor growth in wild-type (WT) mice." (PMID 26388427, 2015). "Our current study presents an additional role for the mechanosensitive ion channel TRPV4 in the proliferation of TEC, a key event during tumor angiogenesis." (PMID 26388427, 2015). "We argue that the functional interplay between Piezo1, TRPV4 and TRPC1 might have a pathophysiological relevance in PDAC and other tumor entities." (PMID 40019468, 2025). "Indeed, Fang and colleagues described that TRPV4 inhibition in vitro depleted cell proliferation, reduced EMT, and led to apoptosis via downregulation of p-ERK while also suppressing tumor growth in xenograft models in vivo." (PMID 37762011, 2023). "Tumor size was also greatly reduced in the group treated with the combination of a TRPV4 agonist and cisplatin; however, the reduction was not statistically significant." (PMID 36143906, 2022). "TRPV4 and TRPM3 have been shown positively related to tumor progression." (PMID 36588677, 2022). "Thus, exploring the relationship between TRPV4 and TAM is helpful to understand the role of TRPV4 in tumor progression." (PMID 34262942, 2021). "A study investigating mRNA expression levels of the TRP channels in human CRC tissue versus normal colon mucosa detected an increase in gene expression of TRPM8, TRPV6, and TRPV1 and a lower expression of TRPV4, TRPM4, TRPV3, TRPC6, and TRPV5 in the tumor tissues of CRC compared to normal tissues." (PMID 32182937, 2020). "Accordingly, overexpression or pharmacological stimulation of TRPV4 with GSK1016790A has been shown to lead to a “normalization” of the vascular endothelium, enhancing the permeability of chemotherapeutic drugs, and basically blocking tumor growth." (PMID 33132914, 2020). "Finally, we discuss the role of endothelial TRP channels in aberrant tumor vascularization by focusing on TRPC1, TRPC3, TRPV2, TRPV4, TRPM8, and TRPA1." (PMID 32038296, 2019). "In previous studies, it was demonstrated that TRPV4 was highly expressed in tumor-derived endothelial cells and the absence of TRPV4 induced increased vascular density and enhanced tumor growth in lung cancer." (PMID 31189890, 2019). "Moreover, the daily intraperitoneal delivery of GSK improved pericyte coverage in TRPV4 KO mice xenografted with LLC cells and favored cisplatin-induced tumor shrinkage." (PMID 32038296, 2019). "Samples with either TRPV4, KRAS, or FGFR1 mutations had strong phospho-ERK staining in a large component of the mononuclear cells in the tumor, while the multinucleated giant cells were negative, as expected." (PMID 30385747, 2018).
tumor (continued). "Recently, we found low functional levels of TRPV4 in TEC, which may contribute to constitutively active Rho, abnormal mechanosensing, and tumor angiogenesis exhibited by these cells." (PMID 27029071, 2016). "In the present study, we demonstrate that reduced expression of the mechanosensitive ion channel TRPV4 in TEC results in increased proliferation, which may contribute to abnormal tumor angiogenesis." (PMID 26388427, 2015). "Understanding the functional significance and molecular signaling behind the TRPV4-dependent regulation of TEC proliferation and tumor angiogenesis could provide a novel avenue for anti-angiogenic or vascular normalization therapies." (PMID 26388427, 2015). "It is unclear whether the normalization of tumor vasculature is a unique function of TRPV4 but not other mechanosensors." (PMID 35331296, 2022). "However, the mechanisms by which tumors or the tumor microenvironment downregulate TRPV4 channels and influences angiogenesis in vivo, are not known." (PMID 35004649, 2021). "On the other hand, an overexpression on TEC could be exploited for a tumor targeted therapy based on lower inhibiting doses of TRPV4 antagonists which could selectively affect TEC and not normal EC." (PMID 24204345, 2013). "However, whether and how the tumor microenvironment downregulates TRPV4 and transforms the normal endothelial cell phenotype remains unknown." (PMID 31921855, 2019). "Unlike B-TECs, TRPV4 was down-regulated in A-TECs, which increased their sensitivity towards extracellular matrix stiffness, boosted their migration rate and favored the development of an aberrant (i.e., non-uniform, abnormally dilated and leaky) tumor vascular network." (PMID 29324706, 2018). "Therefore, to determine if the Rho/Rho kinase pathway is modulated by TRPV4-dependent mechanotransduction, we measured Rho activity and found that the absence of TRPV4 significantly increases basal Rho, suggesting that TRPV4 may regulates tumor angiogenesis by maintaining optimal levels of Rho." (PMID 27029071, 2016). "While LLC cells express TRPV4 (NEC were used as a positive control), treatment with TRPV4 activator GSK did not affect proliferation, confirming that GSK specifically inhibits proliferation of TEC, but not tumor epithelial cells." (PMID 26388427, 2015).